TUBB2A (tubulin beta 2A class IIa)
Description:
Tubulin is the major constituent of microtubules, a cylinder consisting of laterally associated linear protofilaments composed of alpha- and beta-tubulin heterodimers. Microtubules grow by the addition of GTP-tubulin dimers to the microtubule end, where a stabilizing cap forms. Below the cap, tubulin dimers are in GDP-bound state, owing to GTPase activity of alpha-tubulin.
Synonyms: TUBB2; dJ40E16.7; CDCBM5; TUBB
Tractability: Small molecule: an approved drug acts on it; a structure with a bound ligand is known; a high-quality ligand is known; it belongs to a druggable protein family. PROTAC: UniProt records ubiquitination sites on it; ubiquitination databases record sites on it; its protein half-life has been measured; a small molecule that binds it is known. Other modalities: an approved drug acts on it.
Target class: Structural protein
Gene: Protein-coding gene on chromosome 6 (3,153,497 to 3,157,544, reverse strand). Ensembl gene ENSG00000137267.
Subcellular location: Cytoplasm, cytoskeleton
Subcellular location (Human Protein Atlas): Microtubules; Basal body; Cytokinetic bridge; End piece; Flagellar centriole; Mitotic spindle; Primary cilium; Primary cilium tip; Principal piece
Pathways (Reactome):
Cell Cycle: EML4 and NUDC in mitotic spindle formation; Mitotic Prometaphase; Recruitment of NuMA to mitotic centrosomes; Resolution of Sister Chromatid Cohesion; Sealing of the nuclear envelope (NE) by ESCRT-III; Separation of Sister Chromatids; The role of GTSE1 in G2/M progression after G2 checkpoint
Vesicle-mediated transport: COPI-dependent Golgi-to-ER retrograde traffic; COPI-independent Golgi-to-ER retrograde traffic; COPI-mediated anterograde transport; Gap junction assembly; Microtubule-dependent trafficking of connexons from Golgi to the plasma membrane; Translocation of SLC2A4 (GLUT4) to the plasma membrane
Metabolism of proteins: Carboxyterminal post-translational modifications of tubulin; Formation of tubulin folding intermediates by CCT/TriC; Post-chaperonin tubulin folding pathway; Prefoldin mediated transfer of substrate to CCT/TriC
Signal Transduction: Hedgehog 'off' state; RHO GTPases Activate Formins; RHO GTPases activate IQGAPs
Immune System: MHC class II antigen presentation; PKR-mediated signaling
Neuronal System: Activation of AMPK downstream of NMDARs; Assembly and cell surface presentation of NMDA receptors
Organelle biogenesis and maintenance: Cargo trafficking to the periciliary membrane; Intraflagellar transport
Autophagy: Aggrephagy
Cellular responses to stimuli: HSP90 chaperone cycle for steroid hormone receptors (SHR) in the presence of ligand
Developmental Biology: Recycling pathway of L1
Disease: HCMV Early Events
Hemostasis: Kinesins
Gene Ontology:
Molecular function: protein binding; GTP binding; structural constituent of cytoskeleton; GTPase activity
Biological process: mitotic cell cycle; neuron migration; cerebral cortex development; cytoskeleton organization; microtubule-based process
Cellular component: ciliary tip; cilium; extracellular exosome; extracellular vesicle; intercellular bridge; microtubule; microtubule cytoskeleton; mitotic spindle; nucleus; sperm end piece; sperm principal piece; cytoskeleton
Genetic constraint (gnomAD): Loss-of-function variants: 6 observed, 26.35 expected, observed/expected ratio (o/e) 0.23, 90% interval 0.12 to 0.45. The upper end of that interval is the gene's LOEUF score, 0.45, which puts it in group 1 of 6, group 1 being the genes least tolerant of losing a copy. Missense variants: 68 observed, 397.06 expected, observed/expected ratio (o/e) 0.17, 90% interval 0.14 to 0.21. Synonymous variants: 139 observed, 153.85 expected, observed/expected ratio (o/e) 0.9, 90% interval 0.79 to 1.04.
Gene-disease validity (ClinGen):
ClinGen rates the evidence that TUBB2A causes each of these diseases.
tubulinopathy (autosomal dominant): Definitive. A nervous system disorder characterized by complex cortical malformations including in most cases dysmorphic basal ganglia and/or corpus callosum in which the cause of the disease is a variation in a tubulin gene.
Homologues: Orthologues: mouse Tubb2a (100% identical), pig TUBB2A (100% identical), rat Tubb2a (100% identical), zebrafish tubb2 (96% identical), Drosophila melanogaster betaTub85D (95% identical), rabbit TUBB2A (84% identical). Paralogues in human: TUBB2B (99% identical), TUBB4B (96% identical), TUBB (95% identical), TUBB4A (95% identical), TUBB3 (92% identical), TUBB6 (91% identical), TUBB8 (88% identical), TUBB8B (87% identical), TUBB1 (80% identical), TUBA1B (42% identical), TUBA1A (42% identical), TUBA1C (42% identical), and 11 more.
Diseases named in the same sentence as TUBB2A in open-access papers:
TUBB2A is named in the same sentence as 73 diseases in open-access papers, as found by Europe PMC text mining. Sharing a sentence is not in itself a finding about the gene and the disease. The quoted sentences say what the papers report.
gastric cancer (10 papers, 2017 to 2024). A primary or metastatic malignant neoplasm involving the stomach. "LncRNA KRTAP5‐AS1 and TUBB2A regulate CLDN4 expression by acting as a sponge to adsorb miR‐596 or miR‐3620‐3p in gastric cancer." (PMID 32364663, 2020). "The expression of EIF4E, EXOSC1, IARS1, IGFBP1, and SPCS1 was found to be upregulated in stomach cancer cell lines, while TSPYL2 and TUBB2A showed downregulated expression." (PMID 38700505, 2024).
tubulinopathies (10 papers, 2019 to 2025). "Mutations in tuba1a, tubb2a, and tuba4a have all been linked to a group of clinical neurodevelopmental disorders known as tubulinopathies." (PMID 39453165, 2024). "We report two new tubulinopathy cases linked to de novo, heterozygous T178M missense mutations in either the TUBB2A or TUBB3 β-tubulin isotypes." (PMID 34869359, 2021). "We describe two patients with analogous T178M mutations in either the TUBB2A or TUBB3 β-tubulin isotypes exhibiting cortical malformations consistent with tubulinopathies." (PMID 34869359, 2021). "TUBB2A, a neuron-specific beta-tubulin isotype with 90% homology to TUBB2B, is also associated with tubulinopathies." (PMID 41503485, 2025). "Mutations in seven genes encoding α- (TUBA1A), β- (TUBB2A, TUBB2B, TUBB3, TUBB4A, TUBB5), and γ- (TUBG1) microtubulin are linked to extensive overlapping brain malformations or tubulinopathies." (PMID 40948494, 2025). "In fact, primary neurodegenerative tubulinopathies, caused mainly by mutations in genes encoding the components of the tubulin cytoskeleton, especially in TUBA4A, TUBB2A, and TUBB3 genes, have been excellently reviewed and comprehensively discussed recently." (PMID 36352320, 2023). "We identified a TUBB6 p.(Glu410Lys) variant in syndromic familial ptosis pedigree ENG_CML; this substitution has been reported as P/LP for tubulinopathies in four paralogs (TUBB2A, TUBB2B, TUBB3, and TUBB4A; ClinVar Variation IDs: 986830, 1195195, 6967, 135658)." (PMID 38585811, 2024). "These can be either primary neurodegenerative tubulinopathies (caused by mutations in genes coding for components of microtubules, like TUBA4A, TUBB2A, and TUBB3) or disorders caused by various pathogenic interactions and transactions between different compounds and tubulin cytoskeleton." (PMID 36352320, 2023). "However, neither loss of Tubb2a nor Tubb2b results in the severe cortical malformations seen in the most common tubulinopathy patients." (PMID 31386652, 2019). "Other “tubulinopathies” genes include TUBA1A, TUBB2A, TUBB2B, TUBA8, TUBB3, TUBB, and TUBG1, which were found to be DEGAs in various brain regions." (PMID 34638726, 2021).
brain malformations (4 papers, 2015 to 2025). "These included enhancers linked to the disease genes MACF1 (OMIM #618325) and TUBB2A (OMIM #615763), of which coding pathogenic mutations cause brain malformations, and C12orf4 (OMIM #618221) of which bi-allelic variants cause intellectual disability." (PMID 34663447, 2021).
breast carcinoma (4 papers, 2017 to 2025). "Several studies have reported an association between TUBB2A expression and poor prognosis in various cancer types, including breast cancer, pancreatic cancer, and non-small cell lung cancer." (PMID 38891892, 2024). "One study found that TUBB2A overexpression led to increased microtubule stability and resistance to paclitaxel-induced cell death in breast cancer cells." (PMID 38891892, 2024). "Based on the criteria, LTF and TUBB2A were selected as important protein targets for validation of their function in relation to distant metastasis of breast cancer." (PMID 32489334, 2020). "Furthermore, increased TUBB2A expression has been correlated with decreased drug sensitivity in paclitaxel-resistant breast cancer cells." (PMID 28406185, 2017). "Considering the expression level of TUBB2A in the higher-invasiveness group and the high malignancy of distant metastatic breast cancer, the upregulation of TUBB2A might promote the invasion of breast cancer cells, inducing the potential of distant metastatic breast cancer." (PMID 32489334, 2020). "In addition, based on the results of the invasion and migration assay, we verified that the high expression of TUBB2A increases the mobility of breast cancer cells, providing further support for TUBB2A as a novel biomarker candidate of distant metastatic breast cancer." (PMID 32489334, 2020). "Thus, TUBB2A might be a key protein that controls the migration of breast cancer cells from a primary tumor." (PMID 32489334, 2020). "Based on these functions, TUBB2A might control the mobility of distant metastatic breast cancer by regulating the adhesion and proliferation of breast cancer cells, and LTF might govern the death of breast cancer cells and the immune system during distant metastasis." (PMID 32489334, 2020). "The difference in the expression of TUBB2A and LTF was validated by RT-PCR in 1 normal breast cell line and 13 breast cancer cell lines, the relative invasiveness of which was determined per other studies." (PMID 32489334, 2020). "TUBB2A was upregulated in more invasive breast cancer cell lines (i.e., BC cell lines in the higher invasive group), whereas the expression patterns of LTF were perturbed across breast cancer cell lines by RT-PCR." (PMID 32489334, 2020).
cortical dysplasia (4 papers, 2020 to 2024). "Defects of TUBB2A and TUBB2B genes are linked to cortical dysplasia in combination with other brain malformations type 5 and type 7, respectively." (PMID 35911393, 2022).
microcephaly (4 papers, 2018 to 2025). A congenital or acquired developmental disorder in which the circumference of the head is smaller than normal for the person's age and sex. "The association between microcephaly, polymicrogyria and cerebellar agenesis prompted us to screen for tubulin genes (TUBA1A, TUBA8, TUBB2A, TUBB2B, TUBB3, TUBB4A, TUBB, TUBG1), which were all negative." (PMID 35162247, 2022). "Microtubule structure alterations as well as alterations of binding partners necessary for proper microtubule dynamics resulting from pathogenic variants in TUBA1A, TUBB2A, TUBB2B, TUBB3, TUBB5, TUBG1 and TUBA8 genes are also responsible microcephaly and microlissencephaly." (PMID 30340542, 2018).
Parkinson disease (4 papers, 2022 to 2025). A progressive degenerative disorder of the central nervous system characterized by loss of dopamine producing neurons in the substantia nigra and the presence of Lewy bodies in the substantia nigra and locus coeruleus. "Therefore, we speculate that TUBB2A may play an important role in the ongoing case mechanism of AMI by regulating Parkinson disease, gap junction and phagosomes with other mRNAs." (PMID 36600215, 2023). "Noteworthy, TH, dopamine receptor 2 (DRD2), SLC6A3/DAT, SLC18A2, tubulin beta 2A (TUBB2A), tubulin alpha 4A (TUBA4A), and tubulin beta 3 (TUBB3) were the 7 key genes enriched in the Parkinson disease pathway." (PMID 40259945, 2025). "KEGG analysis found that Parkinson disease, gap junction and phagosomes were significantly enriched signaling pathways (FDR < 0.05), and involved multiple DEmRNAs including TUBB2A." (PMID 36600215, 2023).
neuropathy (3 papers, 2014 to 2025). A disorder affecting the nervous system that manifests with pain, tingling, numbness, and/or muscle weakness. "On the other hand, CYP2C8, ABCB1, EPHA5, EPHA6 and TUBB2A were found to be associated with taxane-induced neuropathy in more than one study, but not to be associated with platinum-induced neuropathy." (PMID 26269716, 2015).
Dystonia (2 papers, 2020 to 2022). An abnormally increased muscular tone that causes fixed abnormal postures. "In 3/52 (6%) of the EOA-patients with comorbid dystonia (TTPA, ATP1A3 and TUBB2A gene mutations), both observers had indicated that dystonia was severely present and that dystonia was presented as the main phenotype." (PMID 33255407, 2020).
leukemia (2 papers, 2012 to 2024). A malignant (clonal) hematologic disorder, involving hematopoietic stem cells and characterized by the presence of primitive or atypical myeloid or lymphoid cells in the bone marrow and the blood. "Satb1 has previously been shown to be associated with heightened hematopoietic stem cell (HSC) self-renewal, whereas the role of Tubb2a, Cnn3, Nedd4, and Cand2 in hematopoiesis and/or leukemia is poorly described." (PMID 38555405, 2024). "Moreover, the up-regulation of genes involved in inhibition of apoptosis (e.g. MCL1) may promote the survival of leukemia cells with accumulated DNA damage and their expansion as suggested by an up-regulation of genes involved in cell cycle progression (AHR, AHR, TUBB2A, RAPGEF3, SERTAD1, FLT1)." (PMID 22848414, 2012).
lupus (2 papers, 2022 to 2025). "It is also noted that the 432 dysregulated genes, the IFI27 and TUBB2A co-expression genes were consistently enriched in the disease pathway of systemic lupus erythematosus, which was also activated in the COVID-19 patients compared with their controls." (PMID 34554255, 2022). "For systemic lupus erythematosus (SLE), another uncharacterized disease, TUBB2A was predicted as an activatory target, consistent with its significant downregulation in patients with SLE (P=5.0×10-5)." (PMID 39880378, 2025). "Therefore, we concluded that the IFI27, TUBB2A and the pathways of NET formation and lupus like immune profile may be the potential immune deregulation mechanism triggered by COVID-19, but further experimental validation in vitro and in vivo is needed." (PMID 34554255, 2022).
acute myocardial infarction (1 paper, 2023). Necrosis of the myocardium, as a result of interruption of the blood supply to the area. "Previous studies have found that TUBB2A is up-regulated in acute myocardial infarction, which is consistent with our results." (PMID 36600215, 2023).
Ataxia (1 paper, 2020). Ataxia refers to impaired coordination of voluntary muscle movement. "In two of these patients (ATP1A3 and TUBB2A gene mutations), ataxia had not been identified." (PMID 33255407, 2020). "The two patients in whom none of the observers had recognized ataxia, were diagnosed with an ATP1A3 and TUBB2A mutation, respectively." (PMID 33255407, 2020).
ciliopathy (1 paper, 2021). A genetic disorder of the cellular cilia or the cilia anchoring structures, the basal bodies, or of ciliary function. "We identified 10 genes (STK38L, TUBB2A/B, CCNO, ARL13B, RFX2, RAB23, TUBA1C, CEP170B, and SPATA7) that are established or candidate ciliopathy genes." (PMID 34485842, 2021).
colitis (1 paper, 2025). Inflammation of the colon. "Sera from four patients who developed both skin toxicity and colitis/diarrhea also showed increased autoantibodies to tubulins (TUBB2A, TUBB4A, TUBB, TUBB4B) on treatment." (PMID 40449958, 2025).
COVID-19 (1 paper, 2022). A disease caused by infection with severe acute respiratory syndrome coronavirus 2. "The up-regulation of IFI27 associates with COVID-19 symptomatic infection, which was confirmed by recent studies, but whether the down-regulation of TUBB2A associates with similar clinical scenario requires further confirmation." (PMID 34554255, 2022).
developmental delay (1 paper, 2023). "The only shared HI-gene previously associated with developmental delay is TUBB2A; individuals with pathogenic TUBB2A variants present with developmental delay." (PMID 36964621, 2023). "TUBB2A might thus explain the higher penetrance of developmental delay in patients with larger deletions." (PMID 36964621, 2023).
hypomyelinating leukodystrophy (1 paper, 2023). "The R262H substitution has also been reported in TUBB2A (causing arthrogryposis multiplex congenita) and TUBB4A (causing hypomyelinating leukodystrophy)." (PMID 37600020, 2023). "T178M has also been reported in TUBB2A (causing nervous system abnormality) and TUBB4A (causing hypomyelinating leukodystrophy)." (PMID 37600020, 2023).
Insulin resistance (1 paper, 2019). Increased resistance towards insulin, that is, diminished effectiveness of insulin in reducing blood glucose levels. "The TUBB2A and MRAS are novel biomarkers for the development of insulin resistance." (PMID 30678306, 2019).
lung adenocarcinoma (1 paper, 2022). A carcinoma that arises from the lung and is characterized by the presence of malignant glandular epithelial cells. "However, other five cancer-lncRNA associations, colorectal cancer-CARL, stomach cancer-AF117829.1, breast cancer-AP003486.1, lung adenocarcinoma-AC018413.1 and lung adenocarcinoma-TUBB2A have not been confirmed by the database or literature." (PMID 34983367, 2022).
melanoma (1 paper, 2023). A malignant, usually aggressive tumor composed of atypical, neoplastic melanocytes. "TUBB, TUBB1, TUBB2A, TUBB4A and TUBB4B belong to the tubulin family, and gene expression analyses showed a higher expression of all these tubulins in melanoma compared to normal skin." (PMID 37291228, 2023).
ovarian carcinoma (1 paper, 2017). A malignant neoplasm originating from the surface ovarian epithelium. "In this study we demonstrate that the elevation of Oct4A at the mRNA level correlates with the enhancement in TUBB2A, PLEC and VIM expression in parental HEY, SKOV3 and OVCAR5 ovarian cancer cell lines in response to paclitaxel or cisplatin treatments." (PMID 28406185, 2017).
ovarian tumors (1 paper, 2017). "Even though VIM/PLEC/TUBB2A demonstrated high expression in ovarian tumors (top 1%), no comparison with normal ovarian tissue exists in these databases so no enrichment/fold change can be indicated in tumors." (PMID 28406185, 2017).
periodontitis (1 paper, 2025). An acute or chronic inflammatory process that affects the tissues that surround and support the teeth. "Machine learning models, combined with Gene Set Variation Analysis (GSVA), identified five key genes (RGS1, ACAT2, KDR, TUBB2A, TDO2) linked to periodontitis." (PMID 39935835, 2025).
psoriatic arthritis (1 paper, 2021). Joint inflammation associated with psoriasis. "Several of those have been implicated in pro-inflammatory processes; for example, HLA-C has been associated with RA; RNF182 was previously reported to be over-expressed in RA, and TUBB2A was found to be over-expressed in psoriatic arthritis." (PMID 33461591, 2021).
schizophrenia (1 paper, 2024). A major psychotic disorder characterized by abnormalities in the perception or expression of reality. "(I) Pairwise expression difference (schizophrenia – control) of an exemplar AF-schizophrenia/control cohort DEG (TUBB2A) across all 29 schizophrenia-control pairs in NeuN+ nuclei." (PMID 38648100, 2024). "Expression of the ‘Macroautophagy’ genes AMBRA1, PRKAB1, TUBA1A, TUBB2A, and TUBA4A was restored in the AT-schizophrenia group." (PMID 38648100, 2024).
spastic ataxia (1 paper, 2023). "A similar mechanism has been proposed for the p.Asp417Asn variant in the neuron-specific β-tubulin TUBB2A, also leading to spastic ataxia." (PMID 37418012, 2023).